GLRX3 (glutaredoxin 3)
Description:
Together with BOLA2, acts as a cytosolic iron-sulfur (Fe-S) cluster assembly factor that facilitates [2Fe-2S] cluster insertion into a subset of cytosolic proteins. Acts as a critical negative regulator of cardiac hypertrophy and a positive inotropic regulator (By similarity). Required for hemoglobin maturation. Does not possess any thioredoxin activity since it lacks the conserved motif that is essential for catalytic activity.
Synonyms: PICOT; TXNL2; bA500G10.4; GRX3; GLRX4; GRX4; TXNL3
Tractability: PROTAC: ubiquitination databases record sites on it; its protein half-life has been measured.
Gene: Protein-coding gene on chromosome 10 (130,136,385 to 130,184,521, forward strand). Ensembl gene ENSG00000108010.
Subcellular location: Cytoplasm, cytosol; Cytoplasm, cell cortex; Cytoplasm, myofibril, sarcomere, Z line
Pathways (Reactome):
Transport of small molecules: Iron uptake and transport
Gene Ontology:
Molecular function: 2 iron, 2 sulfur cluster binding; identical protein binding; iron-sulfur cluster chaperone activity; protein binding; RNA binding; protein kinase C binding
Biological process: [2Fe-2S] cluster assembly; cell redox homeostasis; intracellular iron ion homeostasis; iron-sulfur cluster assembly; negative regulation of cardiac muscle hypertrophy; regulation of the force of heart contraction
Cellular component: iron-sulfur cluster assembly complex; cytoplasm; cytosol; nucleus; cell cortex; dendrite; Z disc
Genetic constraint (gnomAD): Loss-of-function variants: 2 observed, 2.05 expected, observed/expected ratio (o/e) 0.98, 90% interval 0.36 to 1.87. That is too few expected variants to judge how well the gene tolerates losing a copy. Missense variants: 112 observed, 75.66 expected, observed/expected ratio (o/e) 1.48, 90% interval 1.27 to 1.73. Synonymous variants: 44 observed, 27.19 expected, observed/expected ratio (o/e) 1.62, 90% interval 1.26 to 1.93.
Homologues: Orthologues: chimpanzee GLRX3 (99% identical), macaque GLRX3 (99% identical), rat Glrx3 (93% identical), dog GLRX3 (90% identical), mouse Glrx3 (90% identical), rabbit GLRX3 (81% identical), tropical clawed frog glrx3 (77% identical), pig GLRX3 (76% identical), zebrafish glrx3 (71% identical), Caenorhabditis elegans glrx-3 (47% identical), Drosophila melanogaster Grx3 (31% identical). Paralogues in human: GLRX5 (16% identical).
Diseases named in the same sentence as GLRX3 in open-access papers:
GLRX3 is named in the same sentence as 39 diseases in open-access papers, as found by Europe PMC text mining. Sharing a sentence is not in itself a finding about the gene and the disease. The quoted sentences say what the papers report.
cardiac hypertrophy (11 papers, 2013 to 2025). "The mammalian GLRX3/PICOT (ortholog of C. elegans GLRX-3) is involved in immune cell activation, development of cardiac hypertrophy, embryonic development and post-embryonic growth." (PMID 35216131, 2022). "Deletion of Glrx2 in mice hearts results in cardiac hypertrophy and fibrosis as well as hypertension, while Glrx3 KO in mice results in cardiac hypertrophy and heart failure." (PMID 32948023, 2020). "We also listed the differentially expressed proteins involved in cardiac hypertrophy, including glutaredoxin-3 (Glrx3) and collagen alpha-2(I) chain (Col1a2)." (PMID 23671862, 2013). "In another study, Glrx3 overexpression in transgenic mice was found to inhibit cardiac hypertrophy." (PMID 32948023, 2020). "GLRX3, an essential [2Fe–2S]-binding protein, has been reported to play important roles in various signaling pathways including embryogenesis, immune cell response, the regulation of cardiac hypertrophy, cancer cell functions and iron homeostasis." (PMID 24809979, 2014). "In addition to Glrx, Glrx2 and Glrx3 have also been shown to play a role in cardiac hypertrophy." (PMID 32948023, 2020).
lung carcinoma (6 papers, 2015 to 2025). "Further analysis showed that GLRX3 was significantly overexpressed in LUAD and high GLRX3 expression was associated with poor prognosis, consistent with previous reports that GLRX3 is preferentially expressed in lung cancer." (PMID 37254219, 2023). "Moreover, levels of GLRX3 are significantly increased in lung cancer tissues." (PMID 39251997, 2024). "In addition, overexpression of the GLRX3 gene was detected in breast cancer, colon and lung carcinoma, and thus it may serve as a marker for cancer." (PMID 26218761, 2015).
breast carcinoma (4 papers, 2014 to 2021). "A previous report indicated that GLRX3 is involved in epithelial-to-mesenchymal transition (EMT) in breast cancer,; therefore, we examined the changes in EMT marker by GLRX3 knockdown in pancreatic cancer cells." (PMID 34794402, 2021). "Knockdown of GLRX3 in human breast cancer cells reduced NF-κB activity, thereby inhibiting in vitro proliferation, survival, and invasion." (PMID 27203742, 2016). "Overexpression of GLRX3 was observed in human malignancies such as hepatocellular carcinoma, lung and breast cancer." (PMID 27203742, 2016). "GLRX3 also stimulates breast cancer cell growth and metastasis through redox homeostasis and NF-κB signaling." (PMID 26218761, 2015).
colon cancer (3 papers, 2016 to 2022). "For example, the activity of invasion and metastasis of colon cancer cells increased when a splice variant b of the GLRX3 gene (Txl-2b) was expressed, decreased when GLRX3c was expressed, and did not change during GLRX3a expression." (PMID 36552527, 2022). "Recent study has shown that GLRX3 interacts with the PI3K/Akt pathway to promote the motility of colon cancer cells." (PMID 27203742, 2016). "GLRX3 promotes the motility of breast and colon cancer cells." (PMID 27203742, 2016). "Although the complicated roles of GLRX3 in cancer remain poorly understood, overexpression of GLRX3 was ascertained in several types of malignancy, such as nasopharyngeal carcinoma (NPC), oral squamous cell carcinoma (OSCC), colon cancer, and lung cancer." (PMID 34728688, 2021).
nasopharyngeal carcinoma (3 papers, 2016 to 2021). A carcinoma arising from the nasopharyngeal epithelium. "GLRX3 was found to be overexpressed in colon, lung, breast, and nasopharyngeal cancer; GLRX3 expression was also reported to have a positive correlation with patient survival." (PMID 34794402, 2021). "However, the expression and functions of GLRX3 have not been addressed in nasopharyngeal carcinoma (NPC)." (PMID 27203742, 2016).
oral squamous cell carcinoma (3 papers, 2019 to 2021). "In oral squamous cell carcinoma, upregulated GLRX3 promoted cell migration and invasion through the Notch signaling." (PMID 33539420, 2021). "In the PPI network (up regulated), genes such as CUL4A and GLRX3 were responsible for the invasion of many cancer types such as prostate cancer and oral squamous cell carcinoma, but these genes may be identified with the invasion of GBM." (PMID 31137733, 2019).
prostate carcinoma (3 papers, 2015 to 2019). A carcinoma that arises from epithelial cells of the prostate gland. "In addition, 14-3-3 sigma, GLRX3 and DDAH1 have been shown to function in various kinds of tumors as well as prostate cancer." (PMID 26218761, 2015).
asthma (1 paper, 2024). "It protects the lung tissue from oxidative stress, and an altered GLRX3 is known to affect idiopathic pulmonary fibrosis, asthma, and COPD in rodent models or cell-based studies." (PMID 39251997, 2024).
autistic disorder (1 paper, 2012). "Interaction models confirmed a significant association between CTH, glutaredoxin and glutaredoxin 3 and autism (OR = 3.78 (95% CI 2.36-6.04)." (PMID 22524510, 2012).
chronic pancreatitis (1 paper, 2021). A chronic inflammatory process causing damage and fibrosis of the pancreatic parenchyma. "The expression levels of GLRX3 in pancreatic cancer were 8.8-fold greater than those in control plasma (p < 0.001) and 2.8-fold greater than those in chronic pancreatitis (p = 0.005)." (PMID 34794402, 2021). "In western blot analysis, GLRX3 protein expression was increased in the plasma of patients with pancreatic cancer than in the plasma of healthy persons or in patients with chronic pancreatitis." (PMID 34794402, 2021). "GLRX3 expression was increased in the plasma of patients with pancreatic cancer compared to that in the plasma of normal individuals or patients with chronic pancreatitis." (PMID 34794402, 2021).
craniosynostosis (1 paper, 2023). Craniosynostosis is defined as the premature fusion of one or more cranial sutures leading to secondary distortion of skull shape resulting in skull deformities with a variable presentation. "Among the four novel loci (ZIC1, PRKAR1A, AZIN1/ATP6V1C1, GLRX3), there are factors implicated in intramembranous ossification and as we show, inherent to craniosynostosis processes." (PMID 37402774, 2023).
disc degeneration (1 paper, 2025). "In a rat IVDD model, GLRX3-loaded hydrogels mitigated mitochondrial dysfunction, reduced NPC senescence, promoted ECM synthesis, and ameliorated disc degeneration by restoring redox homeostasis." (PMID 41426784, 2025).
hepatocellular carcinoma (1 paper, 2024). A malignant tumor that arises from hepatocytes. "Considering the importance of GLRX3, we validated its role in hepatocellular carcinoma through a series of in vitro experiments." (PMID 39654899, 2024). "Immunohistochemistry experiments indicated that GLRX3 was highly expressed in hepatocellular carcinoma tissues, and Western blot analysis confirmed the elevated protein expression of GLRX3 in these tissues." (PMID 39654899, 2024). "To investigate the relationship between GLRX3 and the invasive migration of hepatocellular carcinoma, we conducted transwell and wound healing assays, revealing that GLRX3 knockdown significantly inhibited the invasive migration of these cells." (PMID 39654899, 2024). "Knocking down the expression level of GLRX3 significantly inhibited the proliferation, invasion, and migration of hepatocellular carcinoma cells." (PMID 39654899, 2024). "Subsequently, CCK8 assays demonstrated that the knockdown of GLRX3 markedly inhibited the activity of hepatocellular carcinoma cells." (PMID 39654899, 2024). "In summary, GLRX3 enhances the invasive migration of hepatocellular carcinoma cells, correlating with the malignant characteristics of the disease." (PMID 39654899, 2024). "This study highlights the critical role of iron metabolism in the progression of hepatocellular carcinoma, particularly the regulatory mechanism of the GLRX3 gene in tumor cell proliferation and immune evasion." (PMID 39654899, 2024). "Finally, we explored the effect of GLRX3 on hepatocellular carcinoma phenotype by in vitro experiments such as PCR, transwell, CCK8, and wound healing assay." (PMID 39654899, 2024).
latent infection (1 paper, 2016). "Hence, GLRX3 overexpression may be involved in the modulation of EBV latent infection in NPC cells, thus contributing to tumorigenesis and progression by reduced immunogenicity of NPC cells." (PMID 27203742, 2016). "GLRX3 inhibits the cellular ROS level, which might contribute to maintaining EBV latent infection and the EMT phenotype in NPC." (PMID 27203742, 2016).
liver cancer (1 paper, 2024). An epithelial or non-epithelial malignant neoplasm that arises from the liver. "Our study also identified GLRX3 (Glutaredoxin 3) as a key iron metabolism target gene that significantly influences liver cancer progression." (PMID 39654899, 2024). "Future research should prioritize elucidating the specific mechanisms through which GLRX3 contributes to tumor progression and developing targeted therapeutic strategies to enhance prognosis and treatment outcomes for liver cancer patients." (PMID 39654899, 2024). "In our study, we observed that GLRX3 was abnormally expressed in liver cancer patients." (PMID 39654899, 2024). "GLRX3, a key regulatory protein for iron-sulfur clusters, is abnormally overexpressed in liver cancer patients, and its overexpression facilitates iron-sulfur cluster assembly and transport, thereby disrupting metabolic balance and promoting tumor cell growth and metastasis." (PMID 39654899, 2024). "Consequently, the expression level of GLRX3 may serve as a significant biomarker for liver cancer prognosis and as a potential indicator for assessing the efficacy of immunotherapy." (PMID 39654899, 2024). "This study revealed that iron metabolism plays a critical role in the progression of liver cancer, focusing on the role of GLRX3 (Glutaredoxin 3) in modulating iron homeostasis and driving tumor progression." (PMID 39654899, 2024). "Third, due to technical and funding constraints, while we investigated the impact of GLRX3 on liver cancer prognosis, we did not conduct a comprehensive analysis of other key iron metabolism genes." (PMID 39654899, 2024).
lung adenocarcinoma (1 paper, 2021). A carcinoma that arises from the lung and is characterized by the presence of malignant glandular epithelial cells. "Our results suggest that CAPN1 and GLRX3 may play important roles in the pathogenesis of lung adenocarcinoma, and that the variants may be useful in predicting the prognosis of lung adenocarcinoma after surgery, thereby helping to refine therapeutic decisions for better clinical outcomes in NSCLC." (PMID 34728688, 2021).
pancreatic cancers (1 paper, 2021). "To verify the function of GLRX3 in pancreatic cancer tumorigenicity in vivo, we injected GLRX3 knockdown or control cells subcutaneously into SCID mice and measured the resulting tumor growth after 14 weeks." (PMID 34794402, 2021). "In pancreatic cancer cells, GLRX3 was increased in spheres compared to adherent cells and was also increased in CD24+/CD44+/ESA+ cells compared to CD24−/CD44−/ESA- cells." (PMID 34794402, 2021). "To investigate the level of GLRX3 expression in human pancreatic cancer cell lines, we performed semi-quantitative RT-PCR and western blot analysis by using various cell lines." (PMID 34794402, 2021). "With the best cut-off value of 28.067 ng/ml, the sensitivity and specificity of GLRX3 to differentiate pancreatic cancer from normal conditions were 80.0 and 100%." (PMID 34794402, 2021). "The median serum levels of GLRX3 in normal conditions and in pancreatic cancer were 13.27 ng/ml (range; 1.94–27.18 ng/ml) and 70.84 ng/ml (range; 7.5–357.64 ng/ml), respectively, with a significant difference (p < 0.0001)." (PMID 34794402, 2021). "The level of GLRX3 expression was elevated in cancer cell lines and in the tissues and blood from patients with pancreatic cancer." (PMID 34794402, 2021). "In our study, GLRX3 overexpression was consistently detected in the blood of patients with pancreatic cancer and in the media of cultured cells as well as in the tissues of patients with pancreatic cancer." (PMID 34794402, 2021). "Next, the correlation of plasma GLRX3 levels with patient survival were evaluated among patients with pancreatic cancer." (PMID 34794402, 2021). "To confirm the potential of GLRX3 as a secretory biomarker for pancreatic tumor initiating cells, we examined GLRX3 in patient plasma samples by western blot analysis." (PMID 34794402, 2021). "In our study, GLRX3 knockdown downregulated the Met/PI3K/AKT pathway in pancreatic cancer cells." (PMID 34794402, 2021). "GLRX3 was partially involved in the EMT process of pancreatic cancer." (PMID 34794402, 2021). "Serum GLRX3 expression was higher in patients with pancreatic cancer than in healthy controls." (PMID 34794402, 2021). "Furthermore, using a commercial ELISA kit, GLRX3 was found to be highly secreted into the serum of patients with pancreatic cancer than in the healthy controls." (PMID 34794402, 2021). "Therefore, we hypothesized that GLRX3 may play a functional role in maintaining self-renewal or stem-like properties in pancreatic cancer." (PMID 34794402, 2021). "To evaluate the potential of serum GLRX3 and CA19–9 levels to differentiate between normal and pancreatic cancer samples, we calculated the area under the curve (AUC) by using a receiver operating characteristic (ROC) curve." (PMID 34794402, 2021). "Thus, GLRX3 may play a role in the CSCs of pancreatic cancer through the c-Met pathway." (PMID 34794402, 2021). "Further, GLRX3 knockdown reduced the level of ABCG2, EMT, and chemo-resistance related proteins in pancreatic cancer cells." (PMID 34794402, 2021). "Using the Pearson’s correlation coefficient and Kaplan-Meier survival estimate, we examined the correlation between GLRX3 mRNA and EMT-related gene expression in human pancreatic cancers in The Cancer Genome Atlas (TCGA) dataset." (PMID 34794402, 2021). "To analyze whether such a correlation might exist, we downloaded the data on GLRX3 and MET mRNA expression levels in human pancreatic cancers available at The Cancer Genome Atlas (TCGA)." (PMID 34794402, 2021). "There were no previous reports about the role of GLRX3 in pancreatic cancer; however, relatively high expression of GLRX3 mRNA expression was associated with the poor survival of PDAC patients in TCGA." (PMID 34794402, 2021). "When GLRX3 was downregulated using shRNA and siRNA in a pancreatic cancer cell line, c-Met and its downstream molecules such as PI3K and pAKT were decreased; however, c-Met knockdown did not affect GLRX3 expression." (PMID 34794402, 2021).